SYNPO (synaptopodin)
Diseases named in the same sentence as SYNPO in open-access papers (continued):
Sharing a sentence is not in itself a finding about the gene and the disease.
endothelial dysfunction (3 papers, 2013 to 2026). In vascular diseases, endothelial dysfunction is a systemic pathological state of the endothelium (the inner lining of blood vessels) and can be broadly defined as an imbalance between vasodilating and vasoconstricting substances produced by (or acting on) the endothelium. "In an attempt to address the role of endothelial dysfunction in the development and progression of ADR-induced podocyte injury, the expression of eNOS and synaptopodin were examined by Western blotting in kidneys from Balb/c mice." (PMID 23359116, 2013). "Parameters studied were urinary albumin/creatinine ratio (UACR), biomarkers of podocyte damage (synaptopodin, podocalyxin), PT dysfunction (kidney injury molecule-1-KIM-1, N-acetyl-β-(D)-glucosaminidase-NAG), endothelial dysfunction (P-selectin), VEGF, sFlt-1, and PlGF." (PMID 42123337, 2026). "The data provided reveal significant difference between the serum and urine biomarkers of PT dysfunction (KIM-1, NAG), podocyte damage (synaptopodin, podocalyxin), mitochondrial dysfunction (mtDNA), inflammation (SDF-1), endothelial dysfunction (P-selectin), and oxidative stress (AOPPs)." (PMID 40429625, 2025).
nephrosis (3 papers, 2021 to 2025). Pathological processes of the KIDNEY without inflammatory or neoplastic components. "Slit diaphragm-related proteins such as nephrin, podocin and synaptopodin are reduced in pathological conditions such as nephrosis, in which proteinuria is apparent." (PMID 40191205, 2025).
bone cancer (2 papers, 2017 to 2020). A primary or metastatic malignant neoplasm affecting the bone or articular cartilage. "Spinal miRNA-124 regulates SYNPO and nociception in an animal model of bone cancer pain, so SYNPO is upregulated in bone cancer." (PMID 32596394, 2020).
chronic kidney disease (2 papers, 2013 to 2022). Impairment of the renal function secondary to chronic kidney damage persisting for three or more months. "The beneficial effects were associated with reduction of lysine acetylation in 14-3-3β and augmentation of interaction between 14-3-3β and synaptopodin, further extending the clinical potential of Resolvins in the treatment of chronic kidney diseases." (PMID 23840712, 2013). "Elevated levels of ANGII have been identified as a main risk factor for the initiation and progression of chronic kidney disease (CKD); furthermore, increased ANGII concentrations are associated with the downregulation of nephrin and synaptopodin expression in podocytes." (PMID 35406662, 2022).
glioma (2 papers, 2023 to 2024). A benign or malignant brain and spinal cord tumor that arises from glial cells (astrocytes, oligodendrocytes, ependymal cells). "Expression profiling of the peritumoral brain around IDHmut gliomas also showed upregulation of SLC12A5, THBS1, VEGFA, FOSL2, and SYNPO, as has been previously reported in epileptic brain tissue." (PMID 37104042, 2023). "The direct or indirect effects of SYNPO-related brain connectivity on glioma survival was not apparent from our findings." (PMID 38601343, 2024).
glomerulonephritis (2 papers, 2009 to 2016). A renal disorder characterized by damage in the glomeruli. "We compared the expression of three podocyte markers, i.e.: synaptopodin (SYN), CR1 and neprilysin (NEP) in 107 patients with different forms of glomerulonephritis (GN) and 5 normal kidneys (NK)." (PMID 23675111, 2009).
Hyperglycemia (2 papers, 2021 to 2023). An increased concentration of glucose in the blood. "Lithium therapy significantly prevented body weight loss, hyperglycemia and urinary excretion of albumin and NGAL, preserved glomerular expression of SYNPO, and diminished renal expression of NGAL, suggesting a beneficial effect against the STZ injury." (PMID 33478120, 2021). "Whether STZ administration or hyperglycemia altered the expression of p57 or synaptopodin used to identify podocytes is unknown, but in our view, this is unlikely." (PMID 36695822, 2023).
Obesity (2 papers, 2019 to 2021). Accumulation of substantial excess body fat. "The mRNA expression of nephrin, synaptopodin, and CD2AP in urine sediment was not significantly different between the groups, irrespective of the degree of obesity." (PMID 34575240, 2021).
preeclampsia (2 papers, 2012 to 2018). Preeclampsia is a hypertensive disorder of pregnancy that is characterized by new-onset hypertension with proteinuria presenting after 20 weeks of gestation, and depending on mild or severe forms may initially present with severe headache, visual disturbances, and hyperreflexia. "In this study, we sought to describe the presence of podocyturia in preeclampsia and other high risk pregnancy states using the podocyte marker synaptopodin for identification." (PMID 22970373, 2012). "Furthermore, there is evidence that selected podocyte-specific proteins such as nephrin, synaptopodin, and GLEPP-1 are downregulated in preeclampsia, while VEGF and Flt-1 are increased." (PMID 22970373, 2012).
small cell lung carcinoma (2 papers, 2022 to 2023). Small cell lung cancer (SCLC) is a highly aggressive malignant neoplasm, accounting for 10-15% of lung cancer cases, characterized byrapid growth, and early metastasis. "For example, the second most downregulated candidate, SYNPO, coding for synaptopodin, has been discovered to be a transcriptional target of early growth response factor 4 (EGR4) and to contribute to the growth of small cell lung cancer." (PMID 37803350, 2023).
status epilepticus (2 papers, 2017 to 2024). Status epilepticus is defined as a continuous seizure lasting more than 30 min, or two or more seizures without full recovery of consciousness between any of them. "Here, we employed the well-established model of pilocarpine-induced status epilepticus, which can be linked to alterations in memory performance, to study the effects of SE on synaptopodin (SP) and synaptic plasticity." (PMID 28154762, 2017). "A previous study described a notable decrease of Synaptopodin following a status epilepticus." (PMID 39767775, 2024). "Here, we addressed the question of whether pilocarpine-induced status epilepticus affects synaptopodin (SP), an actin-binding protein, which regulates the ability of neurons to express synaptic plasticity." (PMID 28154762, 2017).
cardiac hypertrophy (1 paper, 2017). "Since synaptopodin, a family member of CHAP, has been associated with actin signalling in brain and kidney and since this pathway is involved in cardiac hypertrophy, we investigated the actin signalling pathway in Tg hearts." (PMID 29206857, 2017).
cryptorchidism (1 paper, 2025). The failure of one or both testes of a male fetus to descend from the abdomen into the scrotum during the late part of pregnancy. "The results showed that six target proteins of TJP2, ZO-1, SYNPO2, SYNPO, LMCD1, and MCU showed characteristic distribution in the epididymal tissues of the cryptorchidism group and the normal control group." (PMID 41217791, 2025).
frontotemporal dementia (1 paper, 2017). Frontotemporal dementia (FTD) comprises a group of neurodegenerative disorders, characterized by progressive changes in behavior, executive dysfunction and language impairment, as a result of degeneration of the medial prefrontal and frontoinsular cortices. "Perhaps, as SYNPO is detectable in plasma exosome and it shows lower level in patients with frontotemporal dementia and AD, a similar trend could be obtained in subjects of Lewy body dementias thus making it a potential biomarker candidate." (PMID 28800743, 2017).
HIV-associated nephropathy (1 paper, 2018). Renal disease in human immunodeficiency virus (HIV)-infected patients. "Clinically, reduced expression of synaptopodin has been observed in FSGS, HIV-associated nephropathy (HIVAN), IgA nephropathy, and idiopathic nephrotic syndrome of childhood." (PMID 30255020, 2018).
Hypertension (1 paper, 2024). The presence of chronic increased pressure in the systemic arterial system. "Additionally, we observed a strong co-localization of zyxin with synaptopodin in the foot processes of the podocytes in glomeruli of patients suffering from DN associated with hypertension." (PMID 38605154, 2024).
Immunodeficiency (1 paper, 2021). Failure of the immune system to protect the body adequately from infection, due to the absence or insufficiency of some component process or substance. "ABPs such as gelsolin, Tβ4, filamin, villin-1, gelsolin, profilin-1, SYNPO, and cortactin are abnormally expressed in certain inflammatory environments, where they inhibit or induce immunodeficiency inflammation." (PMID 34194957, 2021).
inflammatory bowel disease (1 paper, 2021). A spectrum of small and large bowel inflammatory diseases of unknown etiology. "The actin-binding protein synaptopodin (SYNPO) also regulates intestinal mucosal susceptibility and permeability and then achieves homeostatic balance in the intestinal tract of inflammatory bowel diseases." (PMID 34194957, 2021).
ischemia (1 paper, 2019). A hypoperfusion of the BLOOD through an organ or tissue caused by a PATHOLOGIC CONSTRICTION or obstruction of its BLOOD VESSELS, or an absence of BLOOD CIRCULATION. "Q-PCR and Western Blot further showed that the mRNA and protein expressions of Synaptopodin, Nephrin, and CD2AP decreased by ischemia in a time-dependent manner, while the expression of TRPC6 mRNA and protein increased in a time-dependent manner." (PMID 30922260, 2019).
Lewy body dementia (1 paper, 2017). A progressive form of dementia characterized by the presence of protein deposits called Lewy bodies in the midbrain and cerebral cortex, and loss of cholinergic and dopaminergic neurons. "We also report SYNPO as a potential candidate biomarker for Lewy Body Dementias." (PMID 28800743, 2017). "The abundance of SYNPO was lower whereas GSTP1 and PLP1 level were higher in Lewy body dementias and its clinical subtypes." (PMID 28800743, 2017).
membranous nephropathy (1 paper, 2024). "However, the determination of individual antibodies alone does not suffice as a sensitive diagnostic test for identifying primary podocytopathies (MCD and FSGS comparing membranous nephropathy), although the diagnostic accuracy of antibodies to synaptopodin appears to be better." (PMID 39544697, 2024). "Since the studied antibodies to annexin 1 and synaptopodin (either alone or in combination) were elevated in the majority of patients with MCD and FSGS, we sought to compare the diagnostic accuracy of these tests for the diagnosis of primary podocytopathies vs. membranous nephropathy." (PMID 39544697, 2024).
nemaline myopathy (1 paper, 2014). Nemaline myopathy (NM) encompasses a large spectrum of myopathies characterized by hypotonia, weakness and depressed or absent deep tendon reflexes, with pathologic evidence of nemaline bodies (rods) on muscle biopsy. "Furthermore, synaptopodin directly binds actin, one of the proteins known to be involved in nemaline myopathy." (PMID 25353622, 2014).
neuropathy (1 paper, 2014). A disorder affecting the nervous system that manifests with pain, tingling, numbness, and/or muscle weakness. "The change in synaptopodin expression is also closely associated with neuropathy." (PMID 24699703, 2014).
non-small cell lung carcinoma (1 paper, 2020). A group of at least three distinct histological types of lung cancer, including non-small cell squamous cell carcinoma, adenocarcinoma, and large cell carcinoma. "A prognostic risk index, grounded on four persister genes (LYNX1, SYNPO, GADD45B, and PDLIM1), was constructed in non-small-cell lung cancer patients from The Cancer Genome Atlas Program (TCGA) using stepwise Cox regression analysis." (PMID 33330109, 2020).
prediabetes (1 paper, 2017). "Moreover, in a study performed in patients with prediabetes and type 2 DM, podocyte marker expression was higher in diabetic subjects as compared to those with prediabetes with regard to mRNA of nephrin, podocin, podocalyxin, synaptopodin, TRPC6, alpha actinin-4, and TGF-β1." (PMID 28484521, 2017).
Proteinuria (1 paper, 2013). Increased levels of protein in the urine. "Proteinuria is the result of various renal disorders in the absence or lack of synaptopodin." (PMID 24260371, 2013).
Renal atrophy (1 paper, 2014). Atrophy of the kidney. "Quantitative assessment demonstrated a decrease in the synaptopodin-positive area in the glomeruli of mice showing macroscopic renal atrophy." (PMID 25244654, 2014). "Immunoblotting demonstrated that podocin and synaptopodin protein levels were significantly reduced in the indoxyl sulfate-treated mice not showing macroscopic renal atrophy." (PMID 25244654, 2014).
renal failure (1 paper, 2018). "Combined with the results of the loss of filtration function, the results suggest that the non-self-healable renal failure due to high transmembrane pressure could be due to the loss of synaptopodin expression and disorganized actin cytoskeleton." (PMID 30424161, 2018).
renal fibrosis (1 paper, 2018). A final common manifestation of a wide variety of chronic kidney diseases characterized by glomerulosclerosis and tubulointerstitial fibrosis. "Treatment with dapagliflozin prevented podocyte injury, glomerular pathology and renal fibrosis determined by second harmonic generation (SHG), nephrin, synaptopodin, collagen IV, and fibronectin immunofluorescence microscopy." (PMID 29301371, 2018). "Administration of dapagliflozin prevented glomerular changes and renal fibrosis determined by PAS staining, SHG microscopy, PSR staining and Collagen IV, nephrin, synaptopodin, fibronectin IF microscopy." (PMID 29301371, 2018).
kidney disease (13 papers, 2013 to 2025). "Variations in the synaptopodin gene (SYNPO) have been associated with susceptibility to kidney diseases." (PMID 41368354, 2025). "Accumulating evidences have suggested that podocytes undergo ferroptosis in progressive kidney disease, which expressed as loss of epithelial markers, such as synaptopodin, together with gaining mesenchymal features (desmin)." (PMID 37819479, 2023). "Expression of synaptopodin declines in a variety of kidney diseases, with changes in the structure and function of podocytes and in the production of proteinuria." (PMID 30922260, 2019). "In kidney disease, therefore, changes of synaptopodin may alter the structure and function of foot processes." (PMID 26161538, 2015). "When considering the upper limit of the reference interval for subjects without kidney disease, it is noteworthy that all patients with MCD tested positive for both anti-annexin 1 and anti-synaptopodin antibodies." (PMID 39544697, 2024).
cancer (8 papers, 2017 to 2025). A tumor composed of atypical neoplastic, often pleomorphic cells that invade other tissues. "The persister gene panel (LYNX1, SYNPO, GADD45B, and PDLIM1) was established and its role to elucidate radio-response and clinical outcome after radiotherapy was subsequently validated across several cancer types." (PMID 33330109, 2020).
infection (4 papers, 2016 to 2025). The state of being infected such as from the introduction of a foreign agent such as serum, vaccine, antigenic substance or organism. "The successful infection decreased the expression of synaptopodin, CD2AP and nephrin and increased that of Snail." (PMID 27571062, 2016). "The eGFP signal was observed from the 3rd week, and the final results showed a robust and continuous expression of eGFP in the kidney cortex and colocalized with Synaptopodin in the glomeruli of the left kidney, suggesting high infection efficacy in glomerular, especially in podocytes." (PMID 35217650, 2022).
tumor (4 papers, 2014 to 2023). "SYNPO has been reported to be an actin-binding protein that functions in actin dynamics, cell migration, and tumor suppression and is exclusively expressed in highly dynamic cell compartments such as kidney podocyte foot processes." (PMID 25411851, 2014).
immune diseases (2 papers, 2021). "Cyclosporin A has been shown to reduce proteinuria in non-immune diseases through several mechanisms and, of particular interest in NS, stabilises podocyte foot processes through increased expression of synaptopodin." (PMID 34031708, 2021).
neurological disorders (1 paper, 2023). "Moreover, supporting RFX7’s potential role in neuronal development and neurological disorders, we identified regulators of neuronal processes among the novel RFX7 targets, such as JUN, SYNPO, PPP3CA, and PPP2R5D." (PMID 36864036, 2023).
SYNPO also shares sentences with these, for which no sentence is quoted: glomerulopathies (4 papers); focal segmental glomerulosclerosis (3); cognitive deficits (2); Glomerular sclerosis (2); IgA nephropathy (2); schizophrenia (2); ANCA-associated vasculitis (1); autism spectrum disorder (1); breast carcinoma (1); depressive disorder (1); heart failure (1); lung carcinoma (1); minimal change disease (1); neuroblastoma (1); neurodegenerative disease (1); pancreatitis (1); Parkinson disease (1); type 2 diabetes mellitus (1).